TRAF7 (TNF receptor associated factor 7)
Diseases named in the same sentence as TRAF7 in open-access papers (continued):
Sharing a sentence is not in itself a finding about the gene and the disease.
cancer (continued). "Truncation and fusion of TRAF7 are rarely detected in human cancers." (PMID 30294322, 2018). "Here, we showed that hypermethylation of TRAF7 is associated with cancer, but not preneoplastic specimens." (PMID 27688749, 2016). "Moreover, the loss of HOXA5 could promote PCa malignancy, EMT phenotype and drive cancer stemness through a previously-unreported TRAF7/HOXA5/SPRY2–MEK/ERK signaling axis." (PMID 37845209, 2023). "The analysis of 33 cancer types revealed that TRAF2, TRAF3, TRAF4, and TRAF7 are predominantly overexpressed, whereas TRAF1, TRAF5, and TRAF6 exhibit lower expression levels." (PMID 38825674, 2024). "TRAF7 has been partially studied in aquatic animals, and BAG3, WDR20 and FUT4 are mostly focused on wound tissue recovery and cancer treatment in medicine." (PMID 35936896, 2022). "Specifically, TRAF7 exhibited the highest average mRNA level among the TRAF family, followed by TRAF4, while TRAF6 showed the lowest average mRNA level according to the TCGA cancer database." (PMID 37389738, 2023). "HOXA5, which is identified as a novel target of TRAF7, has been demonstrated to bind directly to the SPRY2 promoter and subsequently regulate the MEK/ERK signaling pathway, thus to affect PCa proliferation, metastasis, and cancer stemness." (PMID 37845209, 2023). "Here we identified specific CpG sites in L3MBTL1, NKX6-2, PREX1, TRAF7, PRDM14,and NEFM as primarily methylated in cancer specimens but not in other colonic lesions; these genes were also found to be implicated in many important pathways relevant to neoplastic transformation." (PMID 27688749, 2016).
infection (3 papers, 2021 to 2024). The state of being infected such as from the introduction of a foreign agent such as serum, vaccine, antigenic substance or organism. "We demonstrate that Tri1 and TRAF7 specifically interact during infection and that TRAF7 is recruited to the inclusion." (PMID 38814079, 2024). "In this work, we show that Tri1 and TRAF7 specifically interact during infection, and TRAF7 is recruited to the inclusion." (PMID 38814079, 2024). "We thus conclude that in the context of transfection and infection, the interaction between Tri1 and TRAF7 is specific." (PMID 38814079, 2024). "We demonstrate that Tri1 interacts with TRAF7 during infection, and it can recruit endogenous or transfected TRAF7 to the inclusion." (PMID 38814079, 2024). "Together, our results suggest that Tri1 has the capacity to modulate TRAF7 protein-protein interactions (PPIs) and potentially alter TRAF7 signaling during infection." (PMID 38814079, 2024). "Having confirmed that Tri1 and TRAF7 interact during infection, we tested the prediction that Tri1 would recruit TRAF7 to the inclusion." (PMID 38814079, 2024). "The mRNA levels of TRAFs (except TRAF7) were significantly up-regulated in the gill and spleen of Chinese tongue sole after infection with Vibrio harvei and in the liver of black rockfish after infection with Vibrio anguillarum." (PMID 37176078, 2023). "Finally, it will be interesting to determine whether TRAF7 ubiquitin ligase activity and its related pathways are altered in a Tri1-dependent manner during infection." (PMID 38814079, 2024). "In this work, we focused on the TRAF7:MEKK2/3 complexes, but there are other TRAF7 protein-protein interactions that may be altered by Tri1 during infection." (PMID 38814079, 2024). "We observed occasional recruitment of mCh-TRAF7 to the inclusions in infections performed in the absence of inducer, likely due to chromosomally expressed Tri1." (PMID 38814079, 2024).
bacterial infection (1 paper, 2023). "The mRNA levels of TRAF3, TRAF5 and TRAF7 in black rockfish and those of TRAF7 in Chinese tongue sole were down-regulated after bacterial infection, while there was an up-regulation phenomenon in the mRNA level of other TRAFs." (PMID 37176078, 2023).
kidney disorder (1 paper, 2024). A disease involving the kidney. "The level of TRAF7 expression was reduced in all examined kidney disorders compared to normal kidneys, suggesting that this reduction might be attributed to the crucial role of TRAF7 in the formation of endothelium and ciliogenesis, both of which are essential for normal kidney development." (PMID 38927638, 2024).
TRAF7 also shares sentences with these, for which no sentence is quoted: Secretory Meningioma (3 papers); Clear Cell Meningioma (2); intraventricular meningioma (2); ovarian carcinoma (2); benign mesothelioma (1); benign tumors (1); cholangiocarcinoma (1); colon cancer (1); congenital heart disease (1); congenital malformations (1); endotoxemia (1); lymphangioma (1); malignant pleural mesothelioma (1); melanoma (1); meningothelial tumors (1); microcephaly (1); neurodevelopmental disorder (1); ovarian serous cystadenocarcinoma (1); Papillary Meningioma (1); polycystic kidney disease (1); schwannoma (1); scoliosis (1); tubulovillous adenoma (1); uterine corpus endometrial carcinoma (1).